CBLB (Cbl proto-oncogene B)
Diseases named in the same sentence as CBLB in open-access papers (continued):
Sharing a sentence is not in itself a finding about the gene and the disease.
infection (10 papers, 2013 to 2024). The state of being infected such as from the introduction of a foreign agent such as serum, vaccine, antigenic substance or organism. "To summarize, S. aureus initiates an immune escape mechanism in the early stages of infection to colonize the udder, and triggers an inflammatory response that upregulates bta-miR-223 and prevents CBLB expression." (PMID 33195489, 2020). "CAPN5 and CBLB knockout cells displayed similar infection rates through the plasma membrane bypass, while the HCV fusion inhibitor flunarizine reduced infection rates to background levels." (PMID 30024968, 2018). "In contrast, CAPN5 and CBLB were necessary for full infection with all tested HCV genotypes, revealing a pan-genotypic requirement for CAPN5 and CBLB." (PMID 30024968, 2018). "To further investigate a possible role of both proteins in fusion and uncoating, we fused HCVcc particles at the plasma membrane of CAPN5 and CBLB knockout cells by low pH wash and monitored infection rates." (PMID 30024968, 2018). "After 48 h of infection, the levels of inflammatory cytokines in the acinar cavity increased significantly and was accompanied by extensive tissue damage, along with upregulation of CBLB, PI3K, AKT, and p-NF-κB p65 in the mammary glands." (PMID 33195489, 2020). "Consistent with the in vitro findings, the mammary glands of mice infected with 108CFU/100 μL S. aureus showed high levels of CBLB, PI3K, AKT, and p-NF-κB p65 48 h after infection." (PMID 33195489, 2020). "Interestingly, only the immune-regulatory CBLB gene and the multifunctional PRKCB gene were downregulated by infection." (PMID 23425254, 2013). "However, CBLB protein levels did not change significantly during the 48 h infection period and only increased thereafter, whereas PI3K, AKT, and p-NF-κB p65 were upregulated at earlier time points." (PMID 33195489, 2020).
immune disorders (2 papers, 2022 to 2023). "CBL (Cbl proto-oncogene B) proteins had multiple roles in regulating signal transduction, and their absence can mentor malignancy and immune disorders." (PMID 36230417, 2022).
cardiovascular diseases (1 paper, 2024). "This would not only validate our current findings but also open new avenues for understanding the role of CBLB in the broader spectrum of cardiovascular diseases." (PMID 39004726, 2024). "In addition to the systems biology strategies highlighted, we will also explore the effects of CBLB in different contexts of cardiovascular disease." (PMID 39004726, 2024).
CBLB also shares sentences with these, for which no sentence is quoted: systemic lupus erythematosus (9 papers); pancreatic ductal adenocarcinoma (6); Sepsis (5); non-small cell lung carcinoma (4); experimental autoimmune encephalomyelitis (3); juvenile myelomonocytic leukemia (3); lymphoma (3); myeloproliferative disease (3); acute myeloid leukemia (2); allergic asthma (2); allergic disease (2); chronic myelomonocytic leukemia (2); encephalomyelitis (2); hematologic malignancies (2); Hepatic fibrosis (2); inflammation (2); leprosy (2); liver diseases (2); liver inflammation (2); myelodysplastic syndrome (2); myeloid neoplasm (2); myeloproliferative neoplasm (2); Myocardial fibrosis (2); neuroblastoma (2); pancreatic cancer (2); propionic acidemia (2); prostate carcinoma (2); skin cancer (2); acute liver failure (1); acute myocardial infarction (1).
A further 47 diseases each share a sentence with CBLB in 1 paper.